MYC (MYC proto-oncogene, bHLH transcription factor)
Diseases named in the same sentence as MYC in open-access papers (continued):
Sharing a sentence is not in itself a finding about the gene and the disease.
lymphoma (continued). "Recent clinical studies showed that survival of chronic lymphocytic leukaemia (CLL) is largely dependent on BCL2, and that loss of a single Bclx allele attenuates MYC-induced lymphoma in vivo." (PMID 30261081, 2018). "Most of the MYC mutations in lymphomas affect Thr-58, thus changing its phosphorylation and increasing the MYC half-life." (PMID 28375188, 2017). "Host-dependent mechanisms can cause lymphoma regression from MYC inactivation but only in immunocompetent hosts." (PMID 28333115, 2017). "The proto-oncogene MYC is strongly associated with lymphomas and adverse clinical outcomes related to B-cell malignancies." (PMID 28835693, 2017). "A number of cases of this aggressive lymphoma (usually pleomorphic/blastoid variant of MCL) are associated with MYC overexpression, often through MYC translocation to an additional IGH locus." (PMID 28375188, 2017). "We compared communication networks within transformed B cells in different lymphomas affected by overexpressed MYC and conducted a meta-analysis concerning the association of MYC with tumor prognosis in different patient populations." (PMID 28375188, 2017). "MYC is either amplified or shows misexpression in at least 50% of all cancers and a majority of human leukemia and lymphoma cases and SIRT1 is implicated in similar hematological malignancies." (PMID 28674522, 2017). "We report that there was marked selection against Mcl-1 gene loss during c-MYC-driven lymphoma development and a delay in tumor onset." (PMID 26962682, 2016). "The transplantable lymphoma line derives from a primary tumor generated in mice which express the Eμ-MYC transgene which mimics the translocation of MYC to the IgH locus that is diagnostic of Burkitt's lymphoma." (PMID 27590350, 2016). "To explore the impact of B cell-restricted deletion of one or both allele(s) of Mcl-1 on c-MYC-driven lymphoma development, we generated Eμ-Myc mice with one or both Mcl-1 alleles flanked by loxP sites (hereafter called Mcl-1fl/+ or Mcl-1fl/fl, respectively)." (PMID 26962682, 2016). "This is consistent with observations that the loss of a single BCL2L11 allele accelerates lymphoma development in Eμ-MYC transgenic mice." (PMID 27490482, 2016). "A previous animal model study revealed that atorvastatin can inactivate the RAS and ERK1/2 signaling pathways and inhibit the expression of MYC oncogene, which are thought to be closely associated with the development of malignant lymphomas." (PMID 26425850, 2015). "They found lymphoma subtype-specific enhancers in the MYC locus that are silenced in lymphomas with MYC-activating rearrangements and are associated with germline polymorphisms that alter lymphoma risk." (PMID 26640600, 2015). "MYC targets and transcription factors (TF) associated with high gene expression levels give rise to large expression differences between the lymphoma classes but almost negligible methylation effects." (PMID 26371046, 2015). "Similar circuitry has been demonstrated for miR-26a in Burkitt lymphoma cell lines supporting also the existence of an axis of MYC-miR-26a-EZH2-target genes in those lymphomas associated with MYC activation." (PMID 26580594, 2015). "Chromosome translocation of MYC resulting in deregulation occurs most often in lymphoma types associated with aggressive clinical behavior, and in large part MYC deregulation accounts for the aggressive behavior." (PMID 26416427, 2015). "They demonstrated that genetic suppression of MYC in MYC-induced lymphoma resulted in increased senescence associated acidic β - gal staining and heterochromatin formation." (PMID 24796395, 2014). "This EBV-associated lymphoma was one of the first tumours shown to have a chromosomal translocation (chromosome 14) that activates an oncogene (c-MYC)." (PMID 24942062, 2014).
lymphoma (continued). "The oncogenic potential of MYC rearrangements is implicated not only in the initiation of lymphomagenesis but also in its transformation and progression of low-grade lymphomas into a more advanced disease and an unfavorable outcome." (PMID 23369149, 2013). "NFKB2 is also a MYC repression target and Nfkb2 loss has been shown to accelerate lymphoma development in Eμ-Myc transgenic mice." (PMID 23828858, 2013). "This is followed by a review of the literature on lymphoma transformations from underlying FL after acquisition of MYC translocation." (PMID 21736761, 2011). "Herein we reviewed the English literature of high-grade lymphoma transformation from underlying FL upon acquisition of MYC translocation as evidenced by metaphase cytogenetic, FISH or Southern hybridization." (PMID 21736761, 2011). "As an important tumor suppressor gene, inactivating mutations of MGA are common in lymphoma and may lead to high expression of c-Myc by releasing the inhibition of the MYC signaling pathway." (PMID 41561755, 2025). "Moreover, leukemic presentation in DLBCL, although rare, usually associates with aggressive genetic aberrations, notably MYC rearrangements or double-hit/triple-hit lymphoma phenotypes." (PMID 40696688, 2025). "Indeed, the distribution of MYC point mutations in lymphomas recapitulate an aSHM mutation-driven signature." (PMID 41008653, 2025). "The origin of these mutations in lymphomas is uncertain, but MYC is a predicted target of the aberrant somatic hypermutation machinery (aSHM), which displays a high affinity for the genomic regions around the transcription start site (TSS) of transcriptionally active genes." (PMID 41008653, 2025). "MYC is a key TF associated with multiple cancers including EBV-associated lymphomas." (PMID 39599775, 2024). "Moreover, majority of murine lymphoma cells with MYC mutations seem to behave as cancer stem cells able to initiate and sustain tumor development." (PMID 38440231, 2024). "To establish whether computational simulations can accurately predict patient outcomes, we initially simulated the well-characterised subgroup of lymphoma patients with mutations affecting MYC and BCL2 (DH lymphoma)." (PMID 38965209, 2024). "Indeed, MYC is deregulated in a majority of human cancers including lymphoma, and it is usually associated with a poorer outcome." (PMID 39766110, 2024). "However, a 4–6 fold increase in expression of BCL2 and MYC is commonly observed in these genes when they are mutated in lymphoma patient samples." (PMID 38965209, 2024). "Of note, one of the 19 “double-hit” lymphoma cases showed rearrangements with all three FISH probes MYC, BCL2, and BCL6, which falls in the same diagnostic category as cases with MYC and BCL2 rearrangements only but has been called “triple-hit” lymphoma in the literature." (PMID 38903717, 2024). "Overexpression of EZH2 is commonly observed in T lymphomas and linked to the pSTAT3- MYC pathway." (PMID 39284807, 2024). "Additionally, this study revealed that loss of Tfap4, either a single allele or both alleles, accelerated c-MYC-driven lymphoma development in mice." (PMID 36894688, 2023). "DLBCL with rearrangements involving MYC and BCL2/BCL6, which upregulate MYC gene expression, are referred to as double hit or triple hit lymphomas, and are associated with inferior progression free survival and overall survival in patients receiving traditional R-CHOP therapy." (PMID 36818048, 2023). "Additionally, overexpression or translocation of MYC is a common theme across many types of lymphomas, including more aggressive variants of FL, MCL, and SLL/CLL." (PMID 36672402, 2023). "Interestingly, TFAP4 deficient Eμ-MYC lymphomas all arose at the pre-B cell stage of B cell development." (PMID 36894688, 2023).
lymphoma (continued). "Double-hit or Triple-hit lymphoma (DHL/THL) is a subset of high-grade B cell lymphoma harboring rearrangements of MYC and BCL2 and/or BCL6, and usually associate with aggressive profile, while current therapies tend to provide poor clinical outcomes and eventually relapsed." (PMID 36823603, 2023). "Interestingly, the lymphoma-associated MYC oncogene is involved in iron metabolism and can increase intracellular LIP by activating transferrin receptor 1 (TFR1)." (PMID 38007476, 2023). "In this respect, it is notable that increased glutamine flux with MYC activation in the human lymphoma and mouse liver cancer models is associated with increased tumorigenesis that can be attenuated by blocking glutamine utilization either genetically or pharmacologically." (PMID 37639465, 2023). "As TFAP4 is a transcriptional regulator, we next sought to understand how its loss might alter cell signalling pathways to accelerate c-MYC-driven lymphoma development." (PMID 36894688, 2023). "This suggests that human MYC-driven lymphomas, with loss of BAX function that arise in response to BH3-mimetic drug treatment, may still respond to conventional chemotherapeutic agents as salvage therapy." (PMID 36755070, 2023). "Notably, first results from a randomized phase II/III study, the ALLIANCE051701 trial, of DA-EPOCH-R ± Venetoclax in the high-risk arena of MYC/BCL2 DH lymphomas was presented at the ASH 2021 annual meeting." (PMID 35326604, 2022). "In our opinion, the presence of the MYC insertions in BL and other lymphomas might be underestimated, because routine genetic diagnostics are usually based on FISH only, without karyotyping." (PMID 35167621, 2022). "Recently, a group of natural products (Rocaglates) and their synthetic derivatives have been emerging as promising therapeutical agents for the treatment of MYC-associated lymphoma, especially those Double Hit lymphoma with concurrent MYC and BCL2 dysregulation." (PMID 35303910, 2022). "Hence, targeting the mitochondrial ribosome – and ultimately OxPhos activity – provided relevant therapeutic leverage against aggressive MYC‐associated lymphoma." (PMID 36214609, 2022). "We thus hypothesized that, like mitochondrial ribosomes, OxPhos activity might represent a tractable therapeutic target in MYC‐associated lymphoma." (PMID 34632715, 2022). "In addition, a recent study demonstrated that suppression of the E3 ubiquitin ligase UBE3B-mediated MYC ubiquitination and degradation caused by the integration of TRIB3 with MYC is associated with high proliferation and self-renewal of lymphoma cells." (PMID 33652974, 2021). "It has been noted previously in rat fibroblast cell lines that most lymphoma-associated amino acid substitution mutations in MYC reduce its transformation activity in in vitro assays, and these include T58I, which is one of the most frequently occurring lymphoma-associated MYC mutations." (PMID 34885204, 2021). "The T58A and T58I lymphoma-associated mutations affect MYC function differently." (PMID 34885204, 2021). "As would be expected during lymphoma onset, the progressive increase in MYC levels in this study was associated with increased cell growth, entry of the transduced cells into the cell cycle and cell proliferation with increased expression of relevant underlying genes." (PMID 34885204, 2021). "We have used a primary B-cell model to determine how progressively increased MYC levels drive cells, which are otherwise predisposed for oncogenic transformation, into a lymphoma phenotype, as well as how this process is augmented by lymphoma-associated mutations affecting the MYC protein." (PMID 34885204, 2021).
lymphoma (continued). "The most recent revision of lymphoid neoplasms by the WHO recognized a more aggressive, high-grade B-cell lymphoma subtype with a worse prognosis, the ‘double-hit’/‘triple-hit’ (DH/TH) lymphoma, which is characterized by MYC rearrangements that are associated with BCL2 and/or BCL6 rearrangements." (PMID 34207773, 2021). "From the activation of oncogenes such as MYC, some direct consequences are cell growth and proliferation, which may cause lymphoma genesis." (PMID 34572754, 2021). "Also, PRMT5 maintained the expression of the AP1 protein BATF3, which has been described as an upstream MYC-activator in Hodgkin lymphomas and T cell leukemia and is known to cause lymphomas of mature B cells in mice." (PMID 32555249, 2020). "Thus, the lymphoma-promoting roles of TRIB3 are associated with increased MYC stabilization in lymphoma cells." (PMID 33298911, 2020). "The PCM4-reduced interaction and colocalization of MYC-MAX in lymphoma cells may largely be caused by a reduction in MYC abundance induced by PCM4." (PMID 33298911, 2020). "Downregulation of p14arf was shown to inhibit progression of lymphomas with the MYC mutation." (PMID 33553144, 2020). "This study reveals several functional implications for MYC-associated lymphoma therapy." (PMID 33298911, 2020). "Moreover, a loss-of-function mutation of UBE3B (R346Q) is found in MYC-associated lymphoma patients and impedes MYC degradation." (PMID 33298911, 2020). "Indeed in lymphoma, mass spectrometry imaging has identified a unique lipid signature that is characteristic of MYC driven disease, whilst non-MYC lymphoma has a different underlying lipid metabolic profile." (PMID 29541417, 2018). "The recurrent involvement of the miR-17-92 cluster as pathological signature in lymphoma cell lines and tissues suggests that the key factor in determining the miRNA signatures could be linked to MYC action." (PMID 30038718, 2018). "BCL2 promotes cell survival and, in combination with c-MYC expression, confers both proliferation and survival advantages in lymphoma cells, which is part of the underlying biological basis for the more aggressive clinical behavior of the double-expressor lymphomas." (PMID 28379189, 2017). "MYC is linked to apoptosis and lymphoma whereas ZEB1 and CEBPB are enhancer binding proteins." (PMID 28765546, 2017). "Besides having a crucial impact on complex signaling networks in aggressive lymphomas, MYC is also associated with other B cell and plasmacytic neoplasms." (PMID 28375188, 2017). "Furthermore, loss ofCry2 increases the formation of MYC-driven lymphomas in mice with wild-typeCry127." (PMID 29152229, 2017). "MYC is now known to be a potent oncogene and dysregulation of MYC, as a result of gene rearrangement or other mechanism, has been shown to be associated with extremely aggressive clinical behavior in lymphoma patients." (PMID 26416427, 2015). "Ingenuity pathway analysis (IPA) of the molecular and cellular functions associated with newly identified miR-17-19b targets in λ-MYC lymphomas revealed that several pathways relevant for cancer onset and maintenance are affected, including Cell Death and Cell Cycle Regulation." (PMID 26555894, 2015). "Another pathogenic mechanism that may operate in miR-17-92-dependent lymphomas is based on the associations between miR-17-92 over expression and translocations of the MYC gene, an oncogene that is a critical mediator of cell growth." (PMID 25232701, 2014). "Moreover, it has been demonstrated that the down-regulation of miR-29 by MYC, HDAC, and EZH2 promotes cell survival and growth in MYC-associated lymphomas." (PMID 23965974, 2013). "Juxtaposition of MYC with immunoglobulin loci was causally related to development of lymphomas." (PMID 22580498, 2012). "Furthermore, translocations and mutations cause overexpression of oncogenes like BCL2, BCL6 and MYC in lymphoma cells." (PMID 23049692, 2012).
lymphoma (continued). "MYC was previously reported to associate with these promoters in P493 lymphoma cells." (PMID 21941025, 2011). "These mice constitutively express human c-MYC under the control of the murine Eμ enhancer throughout B cell development leading to increased expansion of B cell progenitors that subsequently transform into lymphoma following the acquisition of cooperating oncogenic mutations." (PMID 36894688, 2023). "Notably, MYC activation in aggressive lymphoma was associated with increased CXCR4 expression." (PMID 34363012, 2021). "Furthermore, the iMyc transgene, which accelerated vIL6-dependent disease, may serve as surrogate of human MYC for preclinical studies on MYC-targeted therapies of KSHV-associated lymphoma." (PMID 26918362, 2016). "The demonstration here that Runx activation is virtually essential for MYC transformation of early murine T-cell lymphoma suggests that it may be fruitful to examine the requirement for RUNX function in human leukaemia/lymphomas driven by amplified MYC or NOTCH/IKZF1 mutations." (PMID 24586197, 2014). "Studies over the past couple of years have started to uncover complex genetic and epigenetic mechanisms regulating MYC expression, stability, and function in cancer, including lymphomas, and interrogation of these might shed light on the mechanisms underlying MYC overexpression in CNS DLBCL." (PMID 25479599, 2014). "Moreover, additional MYC translocations in underlying FL may lead to high-grade lymphoma transformations with a wide range of histological subtypes in addition to atypical Burkitt's lymphoma/leukemia." (PMID 21736761, 2011). "This is followed by a comprehensive review of the literature on lymphoma transformations from underlying follicular lymphoma after acquisition of MYC translocation, using Burkitt's lymphoma, follicular lymphoma, transformation and MYC translocations as keywords." (PMID 21736761, 2011). "In aggressive lymphomas, alterations in the MYC oncogene and anti‐apoptotic regulators such as MCL1 and BCL2 are frequent promoters of this phenotype." (PMID 41169010, 2026). "PF‐477736 Chk1i was selected since it was reported to inhibit proliferation in lymphoma cell lines in vitro and in MYC driven lymphoma model." (PMID 40847617, 2025). "This case-to-case variation and weaker correlation of MYC and γH2AX levels in lymphomas, as compared to hemangiosarcomas, paralleled greater variation in overall RNA, protein, and DNA status (genome rearrangements, etc.)." (PMID 40970130, 2025). "The rearrangement of the MYC oncogene is a definitive cytogenetic finding in both double-hit and triple-hit lymphomas." (PMID 40428800, 2025). "PRMT5 is a MYC transcriptional target and is required to sustain MYC-driven lymphoma maintenance through regulation of RNA splicing." (PMID 40377999, 2025). "Prognosis is influenced by stage, Integrated Pulmonary Index (IPI) score, molecular subtype, and genetic rearrangements such as MYC, BCL2, or BCL6, with double-hit lymphomas associated with poorer outcomes." (PMID 41450358, 2025). "Aggressive lymphomas are often characterized by MYC overexpression, which promotes unchecked cell survival and proliferation." (PMID 40321894, 2025). "While most double-hit lymphomas show positivity for MYC and BCL2 proteins and qualify as double-expresser DLBCL, many double-expresser DLBCL cases do not fall under the DH category." (PMID 40428800, 2025).